CLIC4 (CLIC family member 4)
Diseases named in the same sentence as CLIC4 in open-access papers (continued):
Sharing a sentence is not in itself a finding about the gene and the disease.
glioma (6 papers, 2012 to 2024). A benign or malignant brain and spinal cord tumor that arises from glial cells (astrocytes, oligodendrocytes, ependymal cells). "On the one hand, gliomas with high CLIC4 expression have a greater presence of macrophages, neutrophils, and eosinophils; on the other hand, a high CLIC4 expression in gliomas is positively associated with ECM-related genes." (PMID 39595145, 2024). "Gliomas with IDH mutation or 1p19q codeletion express a low level of CLIC4, and a high expression of CLIC4 correlates with poor prognosis." (PMID 39595145, 2024). "Our goal was to investigate the expression levels of CLIC4 and its association with malignancy and prognosis in gliomas." (PMID 39595145, 2024). "Our results suggest that CLIC4 could serve as a novel prognostic biomarker for gliomas, with its expression linked to ECM-related genes and immune cell infiltration within tumors." (PMID 39595145, 2024). "The results showed that glioma cells exhibited higher levels of CLIC4 compared to normal brain tissue (NBT), with glioblastoma (GBM) displaying significantly higher CLIC4 expression than low-grade gliomas (LGG)." (PMID 39595145, 2024). "The results revealed that CLIC4 expression was significantly higher in glioblastoma multiforme (GBM) compared to lower-grade gliomas (WHO II-III)." (PMID 39595145, 2024). "For patients with low-grade gliomas, those with high CLIC4 expression also had a lower OS percentage than patients with low CLIC4 expression in the TCGA, CGGA, and Rembrandt datasets." (PMID 39595145, 2024). "In comparison to glioma cells with lower CLIC4 expression, those exhibiting elevated CLIC4 levels show increased malignancy and a worse prognosis." (PMID 39595145, 2024). "Immune infiltration analysis showed that macrophages and other innate immune cells were predominant in gliomas with high CLIC4 expression." (PMID 39595145, 2024). "The DEGs (differentially expressed genes) in gliomas with high and low CLIC4 expression are enriched in extracellular matrix and immune functions." (PMID 39595145, 2024). "A univariate analysis identified age, WHO classification, IDH status, and CLIC4 expression level as significant factors affecting the survival of glioma patients." (PMID 39595145, 2024). "The analysis above suggests that the transcription level of CLIC4 is related to glioma malignancy and patient prognosis." (PMID 39595145, 2024). "Our results reveal that heightened CLIC4 expression is associated with elevated ECM-related gene activity and the presence of macrophages, neutrophils, and eosinophils infiltrating glioma tissues." (PMID 39595145, 2024). "Consistent with this are studies of head and neck cancers and human gliomas where CLIC4 silencing decreased cell proliferation and increased apoptosis." (PMID 30282979, 2018). "A previous study revealed that the suppression of CLIC4 enhanced the apoptosis induced by H2O2 in glioma C6 cells along with the dissipation of the mitochondrial membrane potential and nuclear translocation of CLIC4 but without the change of Bax/Bcl-2 ratio." (PMID 26816615, 2016). "A recent study reported that the inhibition of CLIC4 triggers mitochondria- and ER stress-mediated apoptosis in human glioma U251 cells under starvation." (PMID 26816615, 2016). "In conclusion, the present study suggests that the CLIC4 protein plays an important role in autophagy and starvation-induced apoptosis in human glioma U251 cells." (PMID 22761775, 2012). "Additionally, immunohistochemical (IHC) analysis revealed that CD68, a macrophage marker, was significantly elevated in glioma tissues with high CLIC4 expression." (PMID 39595145, 2024). "In fact, the recent literature has revealed that CLIC4 may be associated with poor tumor prognosis; however, our study is the first to investigate the role of CLIC4 in glioma prognosis." (PMID 39595145, 2024).
glioma (continued). "However, the role of the CLIC4 gene in glioma remains to be elucidated.In this study, we observed high CLIC4 expression in glioma tissues across six public datasets." (PMID 39595145, 2024). "The results indicated a significant upregulation of CLIC4 in gliomas." (PMID 39595145, 2024). "The results above suggest that CLIC4 plays a critical role in glioma progression and could serve as a potential biomarker for predicting prognosis." (PMID 39595145, 2024). "More aggressive gliomas and mesenchymal GBM are associated with a high expression of CLIC4." (PMID 39595145, 2024). "C6 glioma cells strongly express CLIC4, and it will also be necessary to examine whether the forced expression of CLIC2 and the knockdown of CLIC4 have a synergistic suppressive effect on invasion and metastatic potential." (PMID 36230813, 2022). "However, the correlation between CLIC4 and glioma remains to be uncovered." (PMID 39595145, 2024). "Our findings indicate that a high level of CLIC4 correlates with high expression of ECM-related genes and the infiltration of macrophages, neutrophils, and eosinophils within glioma tissues." (PMID 39595145, 2024). "Although this study revealed the correlation between CLIC4 expression levels and ECM-related genes as well as immune cell infiltration in gliomas, the specific mechanisms require further clarification." (PMID 39595145, 2024). "CLIC4 was found to be overexpressed in high-grade gliomas compared to WHO grade II and III gliomas, a finding that was also confirmed by immunohistochemical (IHC) staining." (PMID 39595145, 2024). "CLIC4 expression levels were positively correlated with specific markers of macrophages (CD80, CD86, MRC1), neutrophils (FCGR3A, FCGR3B), eosinophils (SIGLEC8, IL3RA), T cells (CD3D, CD4), CD8+ T cells (CD8A, CD8D), NK cells (NCAM1), and B cells (CD19) in glioma." (PMID 39595145, 2024).
pulmonary hypertension (4 papers, 2017 to 2025). Increased pressure within the pulmonary circulation due to lung or heart disorder. "Arf6 is a novel effector of CLIC4 and a new therapeutic target in pulmonary hypertension." (PMID 30582444, 2019).
gastric cancer (3 papers, 2011 to 2022). A primary or metastatic malignant neoplasm involving the stomach. "Besides, it serves as a tumor suppressor in gastric cancer and cutaneous squamous cell cancer, as manifested by knockdown CLIC4 facilitates tumor cells migration and invasion." (PMID 35397614, 2022).
breast tumor (2 papers, 2023 to 2025). "For example, the accumulation of cellular ROS, as a signaling module, was increased by deleting CLIC4 from murine 6DT1 breast tumor cells using CRISPR." (PMID 37485065, 2023).
colon cancer (2 papers, 2022 to 2024). "Of the 21 patients with colon cancer, 67.2 % were CLIC4 positive, and CLIC4 expression in colorectal cancer is thought to be related to the distribution of tumor stem-like cells." (PMID 39027429, 2024). "Therefore, in addition to the well characterized role of TGF-β, Wnt-3a and Hh pathways may further drive CLIC4 expression in CAFs as in SSc fibroblasts and colon cancer cells that are shown here." (PMID 35159339, 2022).
cyst (2 papers, 2014 to 2016). A sac-like closed membranous structure that may be empty or contain fluid or amorphous material. "During the course of MDCK cyst maturation, CLIC4 was first found on the cell periphery, with gp135+/Rab11a+ apical vesicles, and then concentrated near the gp135-enriched AMIS juxtaposing Rab11a-labelled REs." (PMID 26786190, 2016). "Consistent with its role in apical exocytosis, CLIC4 is associated with the apical transport cargoes, the EE, the RE, and the apical surface during early luminogenesis of MDCK cyst cultures." (PMID 26786190, 2016).
Hypertension (2 papers, 2022 to 2025). The presence of chronic increased pressure in the systemic arterial system. "In previous experiments in our laboratory with proteomic analysis of renal parenchyma of SHR hypertensive animals, we identified two molecules, namely SGLT2 and CLIC4, associated with the development of hypertension." (PMID 35071703, 2022).
hypertensive nephropathy (2 papers, 2022). Kidney damage that results from chronically elevated blood pressure; complications include glomerular damage resulting in proteinuria and hematuria. "Here, we apply the methodology of targeted proteomic analysis in kidney biopsies from patients with hypertensive nephropathy to study the role of SGLT2 and CLIC4 in the pathogenesis of the disease." (PMID 35071703, 2022).
prostate carcinoma (2 papers, 2022 to 2024). A carcinoma that arises from epithelial cells of the prostate gland. "Similarly, FTO exhibited a suppressive effect on prostate cancer proliferation and metastasis by stabilizing chloride intracellular channel 4 (CLIC4), which encodes a protein that can inhibit cell proliferation through the TGF-β pathway." (PMID 38503745, 2024).
scleroderma (2 papers, 2022). Scleroderma is a rare autoimmune connective tissue disorder characterized by abnormal hardening of the skin and, sometimes, other organs. "Chloride intracellular channel 4 (CLIC4) is a recently discovered driver of fibroblast activation in Scleroderma (SSc) and cancer-associated fibroblasts (CAF)." (PMID 35159339, 2022). "Reports of CLIC4 involvement in the pathogenesis of several human autoimmune diseases, including allergic asthma and scleroderma, add to an expanding awareness of CLIC4 as a mediator of immune function." (PMID 35727842, 2022).
squamous cell carcinoma (2 papers, 2019 to 2020). A carcinoma arising from squamous epithelial cells. "CLIC4 protein expression is diminished in the tumor parenchyma during progression in squamous cell carcinoma (SCC) and other neoplasms, but the underlying mechanisms have not been identified." (PMID 31921386, 2019). "In cancers of epithelial origin, such as squamous cell carcinoma (SCC), CLIC4 levels tend to be reduced in the epithelial compartment with a concomitant upregulation of CLIC4 protein in the nuclei and cytoplasm of tumor-associated stromal cells." (PMID 31921386, 2019).
acute myeloid leukemia (1 paper, 2024). Acute myeloid leukemia (AML) is a group of neoplasms arising from precursor cells committed to the myeloid cell-line differentiation. "Similarly, CLIC4 exhibited distinct enrichments, being predominantly associated with Alzheimer's disease in the high expression group and primarily linked to acute myeloid leukemia in the low expression group (Fig. S9B1, B2)." (PMID 38965390, 2024).
alcohol addiction (1 paper, 2014). "Future experiments using CLIC4 KO mice could help elucidate its potential role in alcohol addiction." (PMID 24886590, 2014).
atrial fibrillation (1 paper, 2026). A disorder characterized by an electrocardiographic finding of a supraventricular arrhythmia characterized by the replacement of consistent P waves by rapid oscillations or fibrillatory waves that vary in size, shape and timing and are accompanied by an irregular ventricular response. "Previous studies have reported the involvement of CLICs (CLIC1, CLIC4, CLIC5) in atrial fibrosis and remodeling in atrial fibrillation (AF)." (PMID 41521401, 2026).
autism (1 paper, 2014). Persistent deficits in social interaction and communication and interaction as well as a markedly restricted repertoire of activity and interest as well as repetitive patterns of behavior. "Changes in CLIC4 expression or subcellular localization are also associated with several pathological conditions including cancer, atopic dermatitis, ethylmalonic encephalopathy, alcoholism and autism, but the functional significance of these changes is still not well defined." (PMID 24886590, 2014). "CLIC4 may participate in other forms of brain pathology, as selective CLIC4 upregulation is detected in brain after experimentally induced stroke and chromosomal transposition of the CLIC4 gene was detected in a patient with autism." (PMID 24886590, 2014).
Autoimmunity (1 paper, 2014). The occurrence of an immune reaction against the organism's own cells or tissues. "The development of spontaneous skin erosions in aging CLIC4 KO mice suggests a potential function for the protein in autoimmunity." (PMID 24886590, 2014).
bladder cancer (1 paper, 2023). "Our research strongly suggests that Sig1R, β-integrin, and CLIC4 interact in bladder cancer cells." (PMID 37199665, 2023).
cardiac hypertrophy (1 paper, 2026). "The study findings further emphasized the possible roles of CLICs, particularly CLIC1, CLIC4, and CLIC5, in cardiac hypertrophy and heart failure." (PMID 41521401, 2026).
COVID-19 (1 paper, 2022). A disease caused by infection with severe acute respiratory syndrome coronavirus 2. "In addition, some mito-DEGs were reversely altered in the AT2 and AT1 subsets (e.g., LRRK2, PID1, SOD2, CLIC4, and ERBB4) or showed altered expression in the AT2 or AT1 subset in patients with COVID-19 (–D)." (PMID 35844544, 2022).
endometriosis (1 paper, 2018). The growth of functional endometrial tissue in anatomic sites outside the uterine body. "They identified CLIC4, RTN4, and VCL as the target genes, and proposed that upregulation of miR-199a in endometriosis regulates adhesion and infiltration of endometrial cells by targeting these genes." (PMID 29463003, 2018).
glioblastoma (1 paper, 2024). The most malignant astrocytic tumor (WHO grade IV). "Similarly, in glioblastoma patients, high CLIC4 expression was associated with a lower OS percentage compared to low CLIC4 expression in the TCGA, CGGA, and Gravendeel datasets." (PMID 39595145, 2024).
heart failure (1 paper, 2026). Inability of the heart to pump blood at an adequate rate to meet tissue metabolic requirements. "Previous studies have reported the involvement of CLICs (CLIC1, CLIC4, and CLIC5) in AF, suggesting that these channels play a broader role in atrial remodeling beyond heart failure." (PMID 41521401, 2026). "We used single‐cell RNA‐seq to demonstrate the significant upregulation of CLIC1, CLIC4, and CLIC5 in a TAC mouse model and patients with DCM, underscoring their conserved roles in heart failure progression." (PMID 41521401, 2026). "Among CLICs, CLIC1, CLIC4, and CLIC5 were significantly upregulated during the hypertrophic and heart failure phases of the TAC mouse model." (PMID 41521401, 2026).
heart valvular diseases (1 paper, 2017). "The alterations of the chloride channels including CLIC1, CLIC4, and CLIC5 occur in both RNA-Seq and iTRAQ studies strongly support that the changes of chloride channels may play an important role in the pathophysiology of AF at least in heart valvular diseases." (PMID 28860555, 2017).
idiopathic pulmonary fibrosis (1 paper, 2024). Idiopathic pulmonary fibrosis (IPF) is a nonneoplastic pulmonary disease that is characterized by the formation of scar tissue within the lungs in the absence of any known cause. "Notably, human PAPCs from idiopathic pulmonary fibrosis (IPF) showed reduced CLIC4 and SMAD3-target genes expression compared to PAPCs from normal lungs." (PMID 39448571, 2024).
kidney injury (1 paper, 2014). Trauma to the kidney. "If this also occurs during TGFβ signaling following acute kidney injury, we would expect to find lower levels of phosphorylated SMADs 2 and 3 in the injured Clic4 null mice than in injured WT mice." (PMID 24708746, 2014). "However, the absence of CLIC4 has no significant impact on the extent of functional recovery or fibrosis following acute injury, indicating that CLIC4 does not play a major non-redundant role in the TGFβ signaling involved in response to acute kidney injury." (PMID 24708746, 2014).
Listeria monocytogenes infection (1 paper, 2022). "Thus, CLIC4 knock-out mice responded to Listeria monocytogenes infection in vivo by producing less inflammatory cytokines and chemokines and were impaired in their ability to clear infection." (PMID 35225986, 2022).
liver fibrosis (1 paper, 2024). "Downregulated Nolc1 and Clic4 are probably among the most important positive effects of NMN in the liver, as it was previously reported that Nolc1 contributes to the activation of hepatic stellate cells, which are key players in the development of liver fibrosis." (PMID 38473844, 2024).
melanoma (1 paper, 2019). A malignant, usually aggressive tumor composed of atypical, neoplastic melanocytes. "Of note, we also checked cBioPortal and found that these proteins related to angiogenesis (i.e. FASN, CLIC4, HSPB1, ARHGEF1, PHGDH, MYO1C, CAV1) are altered in a total of 242 melanoma patients out of a total of 471 (51.36%)." (PMID 31142788, 2019).
mucinous tumors (1 paper, 2018). "Individually, CLIC1 or CLIC4 stained larger percentages of malignant tumors across all EOC subtypes compared with CA125, particularly early stage and mucinous tumors." (PMID 30282979, 2018). "Finally, CA125, but not CLIC1 or CLIC4, showed a significant tumor subtype bias primarily because the mucinous tumors did not stain with CA125." (PMID 30282979, 2018).
Myocardial fibrosis (1 paper, 2026). "In the present study, the upregulation of CLIC1 and CLIC4 in the TAC model and patients with DCM underscores their conserved role in myocardial fibrosis." (PMID 41521401, 2026).
oral squamous cell carcinoma (1 paper, 2023). "Thus, we believe that the low CLIC4 and α-SMA immunoexpression and the significant correlation between their expression can be related to the OVC’s lower invasiveness capacity compared to oral squamous cell carcinoma." (PMID 37026609, 2023).
ovarian tumors (1 paper, 2018). "We previously showed, using a mouse xenograft model, that two members of the chloride intracellular channel (CLIC) protein family, CLIC1 and CLIC4, were produced in xenografted mice by implanted human ovarian tumor cells and shed into the blood." (PMID 30282979, 2018). "Meta-analysis of gene expression levels showed that the mRNA levels of CLIC1 and CLIC4 in normal ovarian surface epithelium, fallopian tube epithelium and ovarian tumors were consistent with the IHC staining patterns." (PMID 30282979, 2018).
pancreatic cancer (1 paper, 2025). "For instance, analysis of early-stage pancreatic cancer samples via single-cell sequencing has identified specific overexpression of genes such as CLIC4 and GAS2L1 in circulating tumor cells." (PMID 41463034, 2025).
psoriasis (1 paper, 2020). An autoimmune condition characterized by red, well-delineated plaques with silvery scales that are usually on the extensor surfaces and scalp. "Therefore, the increased ClIC4 level in fibroblasts from psoriatic patients suggests the role of these cells in enhancing the expression of TGF-β1 in the tissues of people affected by psoriasis." (PMID 32731552, 2020).
skin cancer (1 paper, 2013). "Among them, CLIC4 was found to be involved in skin cancer; however, the exact role of CLIC4 is unclear." (PMID 24053408, 2013).
triple-negative breast carcinoma (1 paper, 2022). An invasive breast carcinoma which is negative for expression of estrogen receptor (ER), progesterone receptor (PR), and human epidermal growth factor receptor 2 (HER2). "TCGA confirmed higher CLIC4 expression in tumors from women under 55 years of age and in triple-negative breast cancers (TNBC) compared to other pathological types." (PMID 35727842, 2022).
virus infections (1 paper, 2019). "We focused on CLIC1 and CLIC4 as candidate channels, due to their known sensitivity to DIDS, 9-ACA and NPPB and involvement in other virus infections such as hepatitis C virus and Merkel cell polyomavirus." (PMID 31483794, 2019).